ADAM10 (ADAM metallopeptidase domain 10)
Diseases named in the same sentence as ADAM10 in open-access papers (continued):
Sharing a sentence is not in itself a finding about the gene and the disease.
hepatocellular carcinoma (continued). "Efficient delivery enabled miR122 to effectively silence ADAM10 mRNA, and miR122 could inhibit the expression of drug efflux transporters, thereby overcoming hepatocellular carcinoma (HCC)’s resistance to PTX and sensitizing HepG2 cells to PTX treatment, and thus synergize with PTX." (PMID 40286130, 2025). "The liver-specific miR-122 that targets both ADAM10 and ADAM17 is decreased in patient with HCC and was recently proposed as a biomarker for hepatocellular carcinoma related to hepatitis C virus infection." (PMID 33805340, 2021). "hUC-MSC-EXs containing miR-451a can limit the EMT of hepatocellular carcinoma (HCC) cells by targeting ADAM10; this may provide a new target for HCC therapy." (PMID 34335792, 2021). "Also in hepatocellular carcinoma (HCC), high levels of ADAM10 protein expression were found, which correlated with disease severity." (PMID 31565100, 2019). "In addition to ADAM9, ADAM10 and ADAM17 are also known to predict poor prognosis in hepatocellular carcinoma and lung cancer, based on previous studies." (PMID 35740916, 2022). "In contrast to our data, revealing that ADAM10 KD alone does not significantly increase caspase-3/7 activity in RB cells, ADAM10 depletion has been shown to increase caspase-3 cleavage of hepatocellular carcinoma cells." (PMID 36293469, 2022). "Collectively, this suggests that ADAM10 levels in hepatoma cells are not limiting HCV infection." (PMID 37967063, 2023).
cognitive deficits (23 papers, 2017 to 2025). "Increased miR-34a expression is associated with cognitive impairment and AD-like pathology by targeting alpha secretase (ADAM10), NMDAR2B and SIRT1 RNAs, whose levels are significantly reduced by miR-34a overexpression." (PMID 38612989, 2024). "In a cohort study of the elderly in Brazil, it was found that the level of ADAM10 was continually decreased with the degree of cognitive impairment, which has the potential as a diagnostic biomarker for AD." (PMID 33942972, 2021). "To identify the underlying mechanisms of ADAM10 for cognitive deficits in the present study, we induced and silenced ADAM10 expression in vitro and in vivo." (PMID 28938628, 2017). "Thus, we conclude that the reduction in ADAM10 by ectopic miR-144 is mechanistically linked to Aβ accumulation-induced cognitive deficits." (PMID 28938628, 2017). "In contrast, overexpression of ADAM10 reversed cognitive deficits caused by miR-144." (PMID 28938628, 2017). "Levels of ADAM10 are reduced in mild cognitive impairment, indicating its role as an early indicator of cognitive impairment." (PMID 39588547, 2024). "The suggested biomarkers are CNTF and ADAM10, which have been clinically investigated in many retinal and cognitive disorders, creating a new pharmacological research venue for enhancing cognitive performance in SSD and ASD." (PMID 39588547, 2024). "Treating patients with cognitive impairment with vitamin A would upregulate ADAM10 and prevent Amyloid Beta formation." (PMID 39588547, 2024). "The possible molecular mechanism for plaque formation in cognitive disorders such as Alzheimer’s is that reduced ADAM10 leads to decreased alpha-secretase." (PMID 39588547, 2024). "More recently, an in vivo study evaluated a peptide capable of restoring the localization and upregulation of ADAM10 activity at the early stages of the disease, hence rescuing cognitive defects, further supporting the therapeutic potential of ADAM10 in AD." (PMID 37266401, 2023). "Conversely, the overexpression of wt ADAM10 in an AD mouse model alleviated cognitive deficits by reducing Aβ accumulation." (PMID 36674432, 2023). "We also found that 117 DEPs, including ADAM10, were closely associated to the AD‐specific β‐amyloid and tau pathologies; and the changes of IDH3B and RTN1 had a potential diagnostic value for cognitive impairment analyzed by machine learning." (PMID 36254251, 2022). "ADAM10 showed the highest connectivity in the whole pathway and a decreased consistency in the central and peripheral during the cognitive impairment process, indicating its important role in AD." (PMID 36254251, 2022). "The up-regulation of ADAM10 in AD model mice prevents formation of Aβ plaques and cognitive deficits." (PMID 34644262, 2021). "Up-regulation of ADAM10 in AD mouse models prevents the formation of senile plaques and cognitive deficits." (PMID 34644262, 2021). "Our data demonstrate for the first time that LIG is able to reduce cerebral Aβ burden and improve cognitive impairment in the APP/PS1 transgenic mouse model of AD via enhancing ADAM10 activity." (PMID 29163135, 2017). "Here, to investigate effects of ADAM10 on Aβ peptides deposition-mediated cognitive deficits, we induced or silenced ADAM10 in TBI rats and N2A cells." (PMID 28938628, 2017). "MWM test demonstrated that overexpression of ADAM10 markedly improved cognitive dysfunction, whereas silencing of ADAM10 significantly aggravated cognitive deficits after TBI." (PMID 28938628, 2017). "Taken together, these findings demonstrated that elevated miR-144 promoted cognitive impairments induced by β-amyloid accumulation post-TBI through suppressing of ADAM10 expression." (PMID 28938628, 2017). "Since ADAM10 is essential for neurons, synapses, brain, and retinal development, impaired ADAM10 in the neurodevelopmental stage might lead to neurodevelopmental disorders characterized as cognitive impairment." (PMID 39588547, 2024).
cognitive deficits (continued). "In addition to its role as a cognitive impairment biomarker, ADAM10 is crucial for normal retina development and was found to be decreased in retinal degenerative disorders." (PMID 39588547, 2024). "An impaired gut function might affect the availability of vitamin A and reduce retinoic acid, leading to the downregulation of ADAM10, which produces Amyloid Beta, leading to retinal degeneration and cognitive impairment." (PMID 39588547, 2024). "Oxidative stress was also reported in ASD, and it is one of the factors that impair ADAM10 function, which might contribute to the pathophysiology of cognitive impairment in ASD patients." (PMID 39588547, 2024). "Treating with an exogenous ADAM10 prevents and might even reverse the amyloidogenic pathways, indicating a possible therapeutic role of ADAM10 for cognitive disorders." (PMID 39588547, 2024). "5- Animal studies have reported the effectiveness of CNTF and ADAM10 in cognitive impairment." (PMID 39588547, 2024). "Moreover, VEGF gain of function has been shown to enhance brain ADAM10 expression in the Tg2576 mouse model of AD, alleviating Aβ load and cognitive deficits." (PMID 38162003, 2023). "Platelet ADAM-10 negatively correlated with the severity of cognitive impairment." (PMID 34440494, 2021). "Considering that ADAM10 increase in plasma is detected as soon as in mild cognitive impairment (MCI) patients, the results presented here may support the complementary clinical use of this biomarker, in addition to the classical AD biomarkers." (PMID 33419480, 2021). "Decrease absorption of vitamin A due to gut or gut microbiota dysfunction, which is known in SSD and ASD, might lead to reduced retinoic acid reaching the retina and decreasing levels of ADAM10, which was also found to be reduced in ASD and SSD, with associated cognitive impairment." (PMID 39588547, 2024). "Moreover, we identified whether miR-144 negatively regulated ADAM10 expression by directly targeting to the 3′ UTR of ADAM10 mRNA, which is closely associated with β-amyloid induced cognitive deficits." (PMID 28938628, 2017). "The downregulation of miR-1251-5p and miR-34a-5p might alleviate cognitive deficit by increasing the activity of disintegrin and metalloprotease 10 (ADAM10), a major α-secretase in brain that is capable of attenuating the production of Aβ by cleavage of APP, resulting in soluble APPα." (PMID 29057267, 2017). "ADAM10 activation by SIRT1 in a mouse model of AD significantly attenuated Aβ deposition and cognitive deficits." (PMID 30249814, 2019). "The results indicated the induction of Aβ formation and cognitive deficits after TBI was mitigated in rats over-expressing ADAM10, and exacerbated in rats silencing ADAM10." (PMID 28938628, 2017). "Additionally, ADAM10 could modulate β-amyloid formation involved in cognitive deficits." (PMID 28938628, 2017). "Furthermore, modulation of the miR‐32533/CREB5 axis ameliorated or worsened cognitive impairment by inhibiting or amplifying Aβ overproduction through the BACE1‐involved amyloidogenic and ADAM10‐involved non‐amyloidogenic pathways." (PMID 39840513, 2025).
melanoma (23 papers, 2008 to 2025). A malignant, usually aggressive tumor composed of atypical, neoplastic melanocytes. "Since ADAM10 suppresses the presentation of the NKG2D ligands for NK cells on the melanoma cell surface, loss of either MITF or ADAM10 increased ligand expression and consequently greatly increased NK cell-mediated cell death." (PMID 33789714, 2021). "We now observe that ADAM10 acts as sheddase of melanoma cell–associated MICA." (PMID 39837817, 2025). "In addition, the release of ADAM10 in EVs by melanoma cells was shown to be linked to a paxillin/integrin interaction and a subsequent shift to lipid rafts, supporting the suggested mechanism for ADAM8 exosomal release." (PMID 35216088, 2022). "Furthermore, PTP4A3 showed a correlation with the expression of several proteases such as ADAM10, which is well-known to be elevated in melanoma metastases, being associated with multiple adhesion molecules that play a crucial role in the development of malignant melanoma." (PMID 39596556, 2024). "In summary, pharmacologic blockade of AR or ADAM10 impairs melanoma-derived spheroid growth and inhibits the invasive phenotype induced by androgens in melanoma cells." (PMID 39837817, 2025). "Bicalutamide and GI254023X revert this effect, further supporting a role for ADAM10 in the androgen-induced motility of melanoma cells." (PMID 39837817, 2025). "On the other, experiments with GI254023X inhibitor strongly support the role of ADAM10 in the androgen-enhanced invasion of melanoma cells and size of derived spheroids." (PMID 39837817, 2025). "Specific blockade of ADAM10 by GI254023X inhibits the hormone effect on MICA expression in melanoma cells and prevents its release, thus counteracting the androgen-induced immune escape." (PMID 39837817, 2025). "NLGN3 is a trophic factor for melanoma cells that is shed from neurons through the action of ADAM10/17." (PMID 41463339, 2025). "Our phosphoproteomic data point to a link between the conserved phosphosite in ADAM10 and T719 and improved survival, mirrored by protein expression in the primary melanoma cohort." (PMID 40075679, 2025). "This occurred through a transfer of ADAM10-activating SPPL3 through melanoma cell dendrites connecting with keratinocytes." (PMID 34502327, 2021). "The observation that MITF controls ADAM10 expression highlights the importance of melanoma phenotype on recognition by the immune system." (PMID 33789714, 2021). "The previous studies revealed that the expression of ADAM10 was overexpressed in a variety of tumors including liver cancer, melanoma, gastric cancer, lung cancer, pancreatic cancer, and bladder cancer." (PMID 32256208, 2020). "The mechanisms by which PAX2 induces EMT are still not well understood, although some studies have suggested that PAX2 regulates ADAM10 expression in cancer cell lines including renal cell carcinoma and melanoma." (PMID 30117015, 2018). "The PAX2 gene plays a vital role in ADAM10 expression, and it has been observed that increased ADAM10 expression via upregulation of PAX2 is associated with melanoma metastasis, attributed to the metalloproteinase activity of the ADAM10 gene." (PMID 29201043, 2017). "A review of the literature (PubMed, 1970–2015; keywords: ADAM-10 and melanoma) revealed only two articles that describe immunohistochemical analysis of ADAM-10 expression in cutaneous melanoma." (PMID 26266086, 2015). "It was revealed that high expression of ADAM-10 positive cells was strictly related with lower intensity of tumor-infiltrating lymphocytes (P = 0.037), which suggests that ADAM-10 regulates immunoresponse in melanoma initiation and progression." (PMID 26266086, 2015). "Downregulation of ADAM10 with siRNA led to a decrease in the growth and migration of melanoma cells." (PMID 25333745, 2015).
melanoma (continued). "The possible meaning of this correlation is unclear and needs further studies, yet it suggests that ADAM-10 is involved in the regulation of immunological response in the initiation and progression of melanoma." (PMID 26266086, 2015). "In human tissue samples we found co-expression of PAX2 and ADAM10 in melanocytes of benign nevi and in melanoma cells of patients with malignant melanoma." (PMID 21876729, 2011). "In contrast to nuclear PAX2, cytoplasmic and membranous ADAM10 expression was detectable in melanocytes and melanoma cells." (PMID 21876729, 2011). "To determine the localisation of PAX2 and ADAM10 we performed immunofluorescence analysis in melanocytes and melanoma cells." (PMID 21876729, 2011). "In summary, we can show that PAX2 can bind to the ADAM10 promoter and regulate ADAM10 protein levels in melanoma cells." (PMID 21876729, 2011). "In summary, our data clearly demonstrate that PAX2 regulates ADAM10 expression in melanoma cells and to our opinion PAX2 represents a new interesting therapeutic target molecule in melanoma." (PMID 21876729, 2011). "To determine the expression levels of PAX2 and ADAM10 in keratinocytes, melanocytes and melanoma cells we performed Western Blot and immunofluorescence analysis." (PMID 21876729, 2011). "Interestingly, a protease named Adam10 (a disintegrin and metalloproteinase domain 10) that acts as a sheddase has been detected in melanoma-derived small prominosomes by a proteome analysis." (PMID 39881297, 2025). "Additionally, hormone stimulation of melanoma cells increases the expression and activation of ADAM10." (PMID 39837817, 2025). "Also, regulation of ADAM10 by PAX2 or miR-320a influences cisplatin sensitivity of melanoma cells and gastric cancer cells, respectively." (PMID 36699085, 2022). "However, while elevated susceptibility to NK-mediated killing was a characteristic of both MITF-KO and ADAM10-KO melanoma cells, a major difference was observed when we performed a vaccination assay." (PMID 33789714, 2021). "Since most ligands of the HER family need to be cleaved from the cell surface by sheddases, we analyzed the cell surface expression of the sheddases ADAM (a disintegrin and metalloprotease) domain 17 (TACE/ADAM17) and ADAM Metallopeptidase Domain 10 (ADAM10) on melanoma cells by flow cytometry." (PMID 33327495, 2020). "ADAM10 was found upregulated in melanoma metastasis compared to primary melanoma." (PMID 24375628, 2014). "Therefore we wanted to characterize PAX2 expression in melanoma and investigate its role in the regulation of ADAM10." (PMID 21876729, 2011). "In addition, with chromatin immunoprecipitation assay, PAX2 overexpression and PAX2 siRNA we present compelling evidence that PAX2 can regulate ADAM10 expression, a metalloproteinase known to play important roles in melanoma metastasis." (PMID 21876729, 2011). "Therefore the downregulation of ADAM10 by PAX2 siRNA in melanoma cells will inhibit the production of soluble L1-CAM and therefore will inhibit the tumor-promoting function of soluble L1-CAM during melanoma progression." (PMID 21876729, 2011). "With immunofluorescence analysis we could confirm that the downregulation of PAX2 led to a decreased ADAM10 expression in melanoma cells." (PMID 21876729, 2011). "Interestingly, we identified with the Transcriptional Element Search System (TESS) a published PAX binding site in the promoter of ADAM10, a metalloproteinase which was significantly overexpressed in melanoma metastasis." (PMID 21876729, 2011). "In summary we can conclude, that melanocytes and melanoma cells in situ co-express ADAM10 and PAX2." (PMID 21876729, 2011). "Quantification of immunofluorescence staining in melanocytes revealed that weak PAX2 expression correlated with weak ADAM10 fluorescence intensity and stronger immunofluorescence staining of PAX2 in melanoma cells was accompanied by increased ADAM10 expression." (PMID 21876729, 2011).